CAV1 (caveolin 1)
Diseases named in the same sentence as CAV1 in open-access papers (continued):
Sharing a sentence is not in itself a finding about the gene and the disease.
Rickettsia infection (1 paper, 2017). "Our results imply that FGFR1 likely interacts with caveolin-1, because Rickettsia infection enhances the association of these proteins." (PMID 28806774, 2017).
Salmonella Infections (1 paper, 2022). Infections with bacteria of the genus SALMONELLA. "In fact, caveolin-1 expression increased the susceptibility of M-cells to Salmonella infection, implicating caveolin-1 in the gateway of microbial pathogen internalization." (PMID 36145318, 2022).
scrapie (1 paper, 2017). A fatal disease of the nervous system in sheep and goats, characterized by pruritus, debility, and locomotor incoordination. "This is in line with previous studies that demonstrated that overexpression of Cav-1 in N2a cells persistently infected with RML scrapie led to a more stable infection." (PMID 28761068, 2017). "Independent of the scrapie strain, PrPSc was recovered from low buoyant density fractions (fractions 4–6) that partially overlapped with Cav-1." (PMID 28761068, 2017).
septic shock (1 paper, 2022). Shock caused by infection; frequently caused by gram negative bacteria, although some cases have been caused by other bacteria, viruses, fungi, and protozoa; characterized by fever, chills, tachycardia, tachypnea, and hypotension. "Caveolin 1 (Cav1) plays a role in the inflammatory signal cascade in the murine LPS-induced septic shock model through the activation of NF-κB, and Cav1−/− mice showed decreased mortality in response to LPS-induced septic shock." (PMID 35628471, 2022).
serous ovarian cancer (1 paper, 2021). "Given the emerging importance of the tumor microenvironment with respect to carcinogenesis and chemoresistance, we evaluated the expression of Cav-1, a key potential regulator, specifically exploring its role in ovarian serous adenocarcinoma as a therapeutic and prognostic factor." (PMID 34813586, 2021).
skin infection (1 paper, 2022). An inflammatory process affecting the skin, caused by bacteria, viruses, parasites, or fungi. "However, only a few studies have reported on CAV-1 and skin infections." (PMID 36532050, 2022). "Since caveolae directly interact with outer pathogens, such as viruses and bacteria, by modulating endocytosis and CAV-1 is expressed in all types of immune cells, CAV-1 is thought to be involved in skin infection." (PMID 36532050, 2022).
small cell carcinoma (1 paper, 2025). A neuroendocrine carcinoma composed of small malignant cells which are often said to resemble "oat cells" under the microscope. "To this end, we perturbed the levels of CAV1 in the cell lines representing two intestine carcinoma types: ECC4, the small-cell carcinoma with a comparably soft phenotype, and TGBC18TKB (TGBC), the adenocarcinoma with a comparatively stiff phenotype." (PMID 39960760, 2025).
Splenomegaly (1 paper, 2018). Abnormal increased size of the spleen. "Cav1-deficient mice exhibited persistent splenomegaly compared to Cav1-heterozygous and WT mice." (PMID 30005686, 2018). "We observed that only Cav1-deficiency is associated with persistent splenomegaly at all timepoints." (PMID 30005686, 2018). "However, as early as 12 weeks, Cav1−/− mice presented with splenomegaly; a finding consistent across all measured timepoints in comparison to WT mice, with Cav1+/− mice mirroring WT mice and no observed sexual dimorphism." (PMID 30005686, 2018). "Both aged Cav1+/− and Cav1−/− mice present with decreased CD19+CD22+ B cells and secondary-follicle atrophy, specifically in the spleen, compared with wild-type controls and irrespective of splenomegaly status." (PMID 30005686, 2018).
Streptococcus pneumoniae infection (1 paper, 2015). "Our results prove the molecular mechanism of well-maintained TLR5 expression and signaling via caveolin-1 upregulation in old macrophages and provide a new model for developing a vaccine adjuvant against pneumococcal infection in the elderly." (PMID 26223660, 2015).
synovial sarcoma (1 paper, 2011). "CAV1 expression was found to be absent or strongly reduced in 3 of 3 fibrosarcomas, 17 of 20 leiomyosarcomas, 5 of 8 angiosarcomas, 15 of 18 malignant fibrous histiocytomas, and 8 of 8 synovial sarcomas." (PMID 21471610, 2011).
T-cell neoplasms (1 paper, 2016). "In addition to carcinogenic challenges in Cav1-null mice, recent studies identify a link between Cav1 and both B- and T-cell neoplasms." (PMID 28018857, 2016). "Taken together, these data suggest a clear role for CAV1 in both B- and T-cell neoplasms." (PMID 28018857, 2016).
ulcer (1 paper, 2014). "One of the major findings reported in this study is that early mucosal repair was delayed significantly as determined by histological examination and macroscopic ulcer index when the Cav1 gene was globally deleted in mice." (PMID 25367694, 2014).
urinary system diseases (1 paper, 2025). "However, there is currently limited research on the role of Cav-1-autophagy in urinary system diseases, and still a lack of sufficient evidence to support its function." (PMID 41030451, 2025).
urolithiasis (1 paper, 2025). Stone(s) within the urinary tract. "CAV1 can mitigate autophagy-dependent ferroptosis, which may consequently reduce calcium oxalate stone formation in urolithiasis." (PMID 40180904, 2025).
uterine carcinoma (1 paper, 2023). A carcinoma involving a uterus. "EphA2 inhibitor dasatinib interferes with the BRAF/CRAF heterodimer activity via elevating caveolin-1 (CAV-1) in uterine carcinoma." (PMID 38111008, 2023).
Vestibular schwannoma (1 paper, 2013). A vestibular schwannoma (also known as acoustic neuroma, acoustic neurinoma, or acoustic neurilemoma) is a benign, usually slow-growing tumor that develops from the VIIIth cranial nerve supplying the inner ear. "Our findings also demonstrate that the MET signaling pathway, which is possibly enhanced by the upstream signaling of SPP1, ITGA4/B6, PLEXNB3/SEMA5A and CAV1, appears to play a paramount role in the development and maintenance of vestibular schwannoma." (PMID 23354516, 2013). "MET and associated genes, such as integrin, alpha 4 (ITGA4)/B6, PLEXNB3/SEMA5 and caveolin-1 (CAV1) showed a clear deregulation in vestibular schwannomas." (PMID 23354516, 2013).
viral hepatitis (1 paper, 2025). An acute or chronic inflammation of the liver parenchyma caused by viruses. "High CAV1 levels were independently associated with poor overall survival (hazard ratio = 1.744, p = 0.044), with the worst prognosis observed patients with viral hepatitis HCC (HBV: hazard ratio = 2.039, p = 0.025, HCV: hazard ratio = 1.768, p = 0.039)." (PMID 40715090, 2025). "CAV1 was significantly overexpressed in HCC tissues from patients with viral hepatitis or cryptogenic origin." (PMID 40715090, 2025).
tumor (772 papers, 2002 to 2026). "High CAV1 expression in tumor cells and low expression in the stroma are associated with poor prognosis and tumor progression." (PMID 40180904, 2025). "The upregulation of CAV1 in tumour tissues and its association with specific stromal constituents underscore its potential as a therapeutic target." (PMID 40715090, 2025). "Pathway analysis further implicated Cav-1 in epithelial-to-mesenchymal transition, cell adhesion, and extracellular matrix remodeling, reinforcing its role in tumor invasiveness." (PMID 40243482, 2025). "In HCC patient datasets, elevated CAV1 mRNA was observed in sorafenib non-responders, and single cell RNA-sequencing of HCC patient tumours revealed a rare population of CAV1+ cancer cells associated with recurrence." (PMID 40715090, 2025). "Collectively, these findings identify CAV1 as a central regulator of tumour dormancy-associated pathways and acquired TKI-resistance through modulation of E-cadherin, RAC1 and p21, alongside activation of the P70S6K and STAT3 pathways." (PMID 40715090, 2025). "Simultaneously utilizing multiple IHC markers allows for the subtyping of tumor and stromal cells, potentially revealing associations between CAV1 protein expression and clinical outcomes specific to particular subsets of tumor and stromal cells." (PMID 38959243, 2024). "In LUAD, CAV1’s expression level and functional status are linked to various biological behaviors, such as the aggressiveness and metastatic capabilities of tumor cells." (PMID 39364312, 2024). "Caveolin-1 (Cav-1), a scaffolding protein located in cytomembrane, which is highly expressed in some kinds of tumors, and is highly associated with tumor associated progression including endocytosis, vesicular transport invasion and metastasis." (PMID 39318372, 2024). "Loss of Cav-1 in human BC stromal cells, particularly, is associated with tumor recurrence, metastasis, and poor prognosis." (PMID 39876898, 2024). "The elevated EV miRNA-3613-3p in the plasma of tumor-bearing mice is associated with Ago2/CAV1 interaction in the tumor cells." (PMID 38649663, 2024). "Further, most findings were confirmed, showing stable associations of CAV1 expression with clinicopathological factors and tumor biology, consistent with the literature." (PMID 38509243, 2024). "ROS released by cancer cells can induce the loss of matrix CAV1, leading to metabolic changes in tumor matrix cells, mitochondrial dysfunction, and further enhancement of mitochondrial autophagy." (PMID 39763653, 2024). "Specifically, Cav1 loss in the stromal compartment predicts poor clinical outcome, including early tumor recurrence, tamoxifen-resistance lymph node metastasis, and poor survival." (PMID 37822942, 2023). "In OSCC, CAV1 is overexpressed and is linked to carcinogenesis, tumor progression, lymph node metastasis, chemoresistance, and poor prognosis." (PMID 37047005, 2023). "This cluster mainly focused on the associations between caveolin-1 overexpression and tumor progression." (PMID 37576808, 2023). "A decrease in Cav-1 is associated with tumour cell growth but also with a high expression of monocarboxylate transporters, such as MCT4 and MCT1 (two promoters of tumour growth and progression under hypoxic conditions)." (PMID 37174088, 2023). "For instance, the reduced expression of caveolin-1 in CAFs is commonly associated with adverse clinical outcomes, including tumor recurrence, metastasis formation, and resistance to chemotherapy." (PMID 38067108, 2023). "Cav1 participates in stem cell differentiation as well as proliferation and cell death pathways, which is implicated in tumor growth and metastasis." (PMID 37998001, 2023). "Second, Cav-1 deficiency also promotes the malignant phenotype of tumors by affecting tumor metabolism." (PMID 37143134, 2023).
tumor (continued). "There is a potential subtlety and context-dependent dichotomy in the reported effects of CAV1, a scaffolding protein which is involved in several cancer-associated processes, that of having both protumorigenic and tumor suppressive roles." (PMID 37046676, 2023). "During the metastatic stage of malignant tumors, CAV1 is involved in adhesion movement, loss of nest apoptosis, and autophagy in tumor cells." (PMID 37907864, 2023). "For example, cancerous cells can obtain lactate and pyruvate from the caveolin-1-deficient stromal fibroblasts for use as energy fuels in the mitochondrial tricarboxylic acid (TCA) cycle to enhance tumor proliferation." (PMID 37681892, 2023). "In fact, the loss of the expression of stromal CAV-1 is a functional marker of autophagy, oxidative stress, and hypoxia in the tumor microenvironment, favoring tumor progression." (PMID 37181035, 2023). "Loss of stromal fibroblast CAV1 by autophagic/lysosomal degradation created a “lethal tumor microenvironment” in a co-culture system, in response to oxidative stress induced by breast cancer cells." (PMID 38234683, 2023). "An increase in glycolysis in cancer-associated fibroblasts and a decrease in CAV1 expression can promote tumor progression." (PMID 37907864, 2023). "The loss of CAV1 within the tumor stroma was accompanied with a loss of stromal PTRF, effects that also correlated with higher Gleason scores, reduced relapse-free survivals, and thus poor outcomes." (PMID 35155239, 2022). "Cytoplasmic CAV1 was associated with a more malignant tumor phenotype, including a strong association with ER negativity, which is consistent with previous studies." (PMID 35660849, 2022). "The extensive documentation of association of stromal loss of CAV1 indicates its value as a prognostic marker and highlights the severity of this alteration on the tumor phenotype." (PMID 35158857, 2022). "CAV1 encodes an integral membrane protein that has been found over-expressed or mutated in solid human tumours and has been shown to be associated with radioresistance." (PMID 35860583, 2022). "At advanced tumor stages however, the gain in epithelial CAV1 was associated with increased invasion and metastasis and also therapy resistance, particularly to RT." (PMID 35155239, 2022). "Further, the loss of CAV1 expression in the tumor stroma leads to the resistance of prostate epithelial cells to radiation." (PMID 35158857, 2022). "We found that the prognostic impact of CAV1 was highly dependent on anthropometric factors associated with a poor metabolic profile and tumor characteristics." (PMID 35660849, 2022). "Collectively, our findings indicate an unexpected role of CAV-1 deficiency in fibroblasts and the tumor microenvironment as a permissive factor, which is regulated by the TGF-β1 signaling pathway in BCCs." (PMID 36604141, 2022). "Positive cytoplasmic CAV1 was associated with several unfavorable tumor characteristics: ER–, PR–, TNBC, histological grade III, and lower frequency of lobular-type tumors (all Padj≤0.002) but was inversely associated with ALNI (Padj = 0.036)." (PMID 35660849, 2022). "This has been termed as the “reverse Warburg effect” indicating that loss of CAV1 drives a switch from oxidative phosphorylation to glycolysis, generating a microenvironment that drives the growth of the adjacent tumor." (PMID 35158857, 2022). "Caveolin-1 is the major essential coat protein for caveolae formation and is implicated in tumoral growth and angiogenesis." (PMID 35722492, 2022). "In recent years, studies related to the role of autophagy and CAFs in the tumor microenvironment have increased and autophagic machinery induction has been associated with the NF-kB pathway and Caveolin-1 (Cav-1) expression in the tumor microenvironment." (PMID 33763351, 2021).
tumor (continued). "CAFs have been shown to regulate T cells through secretion of IL-6 suggesting the higher epithelial Cav-1 expression (and less stromal loss) reflects a tumor microenvironment with fewer CAFs and better immune response." (PMID 34813586, 2021). "Increased tumour expression of Cav-1 was also associated with the IDH-wild type patient cohort with the composite co-variate of high Cav-1 expression and IDH-wild type status producing an extraordinarily powerful and probability of poor outcome (HR = 11.4)." (PMID 34490102, 2021). "The human CAV-1 gene locates at chromosome 7q31.1, and the incidence of tumor suppressor gene loss in high in a broad range of tumor types." (PMID 33935779, 2021). "Subgrouping by histological grade, high Cav-1 tumour expression was associated (P=0.0003) with high-grade GB." (PMID 34490102, 2021). "In particular, while its expression in cancer cells has been associated with an aggressive phenotype and poor prognosis, the loss of Cav-1 in the tumor stroma has been associated with chemoresistance and increased tumor growth." (PMID 34590611, 2021). "Cav-1 was associated with tumor suppression, which is reflected in its ability to arrest the cell cycle and favor apoptosis." (PMID 33774714, 2021). "We found that Doxo treatment was significantly less effective in the CAV1 KD tumor compared with WT tumors, indicating that CAV1 deficiency promotes resistance to Doxo treatment." (PMID 34786475, 2021). "Tumor recurrence is probably linked to the fact that Cav1 maintains/preserves the growth, survival and motility of cells exposed to CTX-radiotherapy." (PMID 34207120, 2021). "HIF1α, NFκB, and loss of Cav-1 have been implicated in the signaling that drives autophagy and catabolism in CAFs that can directly affect tumor growth." (PMID 34376225, 2021). "In recent decades, increasing attention has been paid to the expression of Cav-1 in the tumor stroma where its loss predicts poor outcome." (PMID 33531603, 2021). "Cav-1 staining in GB tumours shows a strong cytoplasmatic/membranous positivity within tumour cells and associated endothelium." (PMID 34490102, 2021). "In the context of cancer, caveolin-1 is the isoform that is mainly associated with tumoral mechanisms, such as malignant transformation, angiogenesis, tumor stage, metastasis, chemotherapeutic response, and prognosis." (PMID 33037799, 2021). "Higher matrix autophagy leads to more severe tumor phenotypes, such as the overexpression of Beclin-1 or the loss of Cav-1 in fibroblasts." (PMID 34503536, 2021). "Here we found increased tumour expression of Cav-1 to be associated with the IDH-wild type patient cohort (P < 0.0001)." (PMID 34490102, 2021). "Mitochondria also play an important role in the loss of caveolin 1 (cav-1) in the tumor-associated fibroblast compartment, which is related to the early tumor recurrence, metastasis, tamoxifen-resistance, and aggravated increase in tumor growth." (PMID 33922139, 2021). "Pathological detection of tumor tissues confirmed that the anti-cancer activities of CP were tightly associated with downregulated expressions of β-catenin, Cav-1, and Vimentin, and upregulation in the expression of E-cadherin." (PMID 34168559, 2021). "The association between the levels of Cav-1 expression and clinicopathologic factors in this study showed a lower Cav-1α expression compared to the expression of Cav-1β through all tumor stages." (PMID 33774714, 2021). "In the Proneural subtype high tumour Cav-1 levels were associated with a significantly shorter survival (high Cav-1 median survival of 12.8 months vs low Cav-1 of 33.6 months)." (PMID 34490102, 2021).